KLF4 (KLF transcription factor 4)
Diseases named in the same sentence as KLF4 in open-access papers (continued):
Sharing a sentence is not in itself a finding about the gene and the disease.
cervical carcinoma (27 papers, 2010 to 2024). A carcinoma arising from either the exocervical squamous epithelium or the endocervical glandular epithelium. "From tumor tissues of 117 patients with locally advanced cervical cancer, KLF4 was disclosed as a risk factor for radioresistance (p = 0.032), poor PFS (p = 0.001), and OS (p < 0.001)." (PMID 37958386, 2023). "Together, these results suggest that KLF4 inactivation in cervical carcinomas results from its promoter methylation." (PMID 24551169, 2014). "KLF4 represses the Wnt signaling pathway, which was shown to be hyperactivated in a subset of cervical cancer." (PMID 24551169, 2014). "KLF4 promoter methylation in cervical cancer cell line was determined by BSQ and methylation-specific polymerase chain reaction (MS-PCR)." (PMID 24551169, 2014). "The average relative expression (compared with GAPDH) of KLF4 was 12.36±2.24 in normal cervix but 1.642±0.31 in cervical carcinoma." (PMID 24551169, 2014). "Normal cervical tissues expressed more than three times KLF4 protein than invasive cervical carcinomas did." (PMID 24551169, 2014). "KLF4 mRNA levels were significantly reduced in cervical cancer tissues compared with normal cervix tissues (P<0.01) and KLF4 mRNA expression showed a significant negative correlation with the promoter hypermethylation (r = −0.486, P = 0.003)." (PMID 24551169, 2014). "Here, we determined that KLF4 promoter methylation was 4-fold higher in cancer samples and also markedly higher in some cervical cancer cell lines, compared with control samples." (PMID 24551169, 2014). "The methylation status of the KLF4 promoter was therefore examined in tissues from normal cervix and cervical carcinoma." (PMID 24551169, 2014). "KLF4 has been shown to interact with a number of pathways with well-documented links to cervical cancer biology." (PMID 24551169, 2014). "In summary, by using the BSQ technology, we uncovered a change in the methylation status of the KLF4 gene in cervical cancer." (PMID 24551169, 2014). "We previously showed that overexpression of KLF4 results in the retardation of cell growth and tumor formation in cervical cancer cells." (PMID 24551169, 2014). "The methylation of the KLF4 promoter region in cervical cancer was different from that of other type of tumors." (PMID 24551169, 2014). "The restored KLF4 expression inhibited the cervical cancer cell survival in the treatment of cisplatin." (PMID 24551169, 2014). "In the present study, the methylation of some CpG islands in the KLF4 promoter was demonstrated in a large subset of cervical cancers, and this methylation was negatively correlated with protein expression." (PMID 24551169, 2014). "In the present study, we assayed the methylation status in the two regions of the KLF4 promoter, and our results suggest that the −1684 to −1878 bp region is hypermethylated in cervical cancer." (PMID 24551169, 2014). "In a previous study, we demonstrated that KLF4 is downregulated during the development and progression of cervical carcinoma." (PMID 24551169, 2014). "Correlation analysis showed that the KLF4 promoter methylation status was inversely related to KLF4 expression at the transcriptional levels in both cervical carcinoma and normal cervix tissues (P = 0.003, r = −0.486)." (PMID 24551169, 2014). "KLF4 transcriptional levels were determined in these 24 cervical carcinoma and 12 normal cervix samples by Real-time PCR." (PMID 24551169, 2014). "KLF4 gene is inactivated by methylation-induced silencing mechanisms in a large subset of cervical carcinomas and KLF4 promoter hypermethylation inactivates the gene’s function as a tumor suppressor in cervical carcinogenesis." (PMID 24551169, 2014). "KLF4 inhibits the proliferation of colon, lung, and cervical carcinoma cell lines by blocking G1/S phase arrest." (PMID 23861801, 2013).
cervical carcinoma (continued). "Moreover, a few KLFs are associated with the effectiveness of tumor treatment and the probability of tumor recurrence: The high KLF4 expression level in cervical cancer is significantly related to resistance to radiation therapy and local recurrence." (PMID 36761967, 2023). "KLF4 expression can predict radiotherapy resistance and poor clinical outcomes for cervical cancer." (PMID 37958386, 2023). "Abnormal expression of other KLFs may indicate the metastases of tumor tissue: The high KLF4 expression level in cervical cancer significantly indicates distant metastasis." (PMID 36761967, 2023). "Hypermethylation of KLF4 gene is happened at enhancer of the gene in human malignant tumor cells; −2,128 ~ −1,770 region in medulloblastoma cells and − 1,852 ~ −1,658 region in cervical carcinoma cells." (PMID 26847634, 2016). "In addition, promoter hypermethylation of KLF4 inhibits the chemosensitivity of cervical carcinoma to cisplatin." (PMID 25605243, 2015). "After treatment with the demethylating agent 5-Azacytidine (5-Aza), the expression of KLF4 in the cervical cancer cell lines at both mRNA and protein levels was drastically increased, the cell proliferation ability was inhibited and the chemosensitivity for cisplatin was significantly increased." (PMID 24551169, 2014). "Normal cervix tissues expressed 6.54 times more KLF4 mRNA than cervical carcinomas did (P<0.05)." (PMID 24551169, 2014). "Moreover, the expression of KLF4 protein and mRNA was restored upon treatment of cervical cancer cell lines with 5-Aza, which inhibited the cell proliferation and increased the chemosensitivity for cisplatin." (PMID 24551169, 2014). "The overexpression of exogenous KLF4 protein was found to inhibit cervical carcinoma cell growth and tumor formation both in vitro and in vivo by activating the cell cycle suppressor p27Kip1, suggesting that KLF4 works as a tumor suppressor in cervical carcinoma." (PMID 24551169, 2014). "Finally, expression of the stem cell self-renewal-associated transcription factors OCT4, NANOG, KLF4 and BMI1 is elevated in ALDHhigh cervical cancer cells." (PMID 24318570, 2013). "Moreover, in cervical cancer cells, Piwil2 overexpression also induced a significant upregulation of c-Myc, Nanog, Oct4, Sox2, and Klf4, increased the proportion of cells that were ALDH, MSCA-1, and ABCG2 positive and subsequently increased cisplatin resistance." (PMID 27602489, 2016). "Evidence indicates that various oncogenes (e.g., LGR5 and DAX1) and suppressor genes (e.g., KLF4 and SLUG) exhibit abnormal expression during cervical carcinoma progression, highlighting the importance of genetic factors." (PMID 39518154, 2024). "Ectopic PIWIL1 overexpression in cervical cancer cells promotes tumor sphere formation by regulating the stem cell-related transcription factors OCT4, NANOG, KLF4, and BMI1, thus conferring resistance to cisplatin." (PMID 35083142, 2021). "It has been reported that some oncogenes and transcription factors are correlated with cervical cancer and likely involved in the development and progression of cervical cancer, such as SOX2, KLF4, OCT4 and NANOG." (PMID 28514765, 2017). "However, it remains unknown how KLF4 is silenced in cervical carcinomas." (PMID 24551169, 2014). "The methylation status of the KLF4 promoter CpG islands was analyzed by bisulfite sequencing (BSQ) in tissues of normal cervix and cervical cancer." (PMID 24551169, 2014). "In fact, real time RT-PCR of HKCs versus a panel of cervical carcinoma and keratinocyte-derived SCC cells showed that, of the several Sp/KLF family members that were examined, Klf4 was strongly and consistently up-regulated in cancer cells." (PMID 20442780, 2010).
cervical carcinoma (continued). "Relevant research showed, trametinib combined with PI3K/mTOR dual inhibitor dactylitis can eliminate the enhancement of nuclear receptor related-1 protein (Nurr1) to cervical cancer cell aggressiveness by upregulating p21 and p27 expression and inhibiting MMP9 and KLF4 expression." (PMID 36204323, 2022). "Conversely, the KLF4 levels were higher in epithelial-like cancer types, such as the head and neck squamous cell carcinoma (HNSC), esophageal carcinoma (ESCA), stomach adenocarcinoma (STAD), and cervical carcinoma (CESC) samples (shown in blue)." (PMID 34680284, 2021). "BMI1 and KLF4 expression levels were found to be elevated in ALDH-high cervical cancer cells that display high stem-like features compared to the ALDH-low cell population, indicating that BMI1 and KLF4 may be CCSC markers." (PMID 27343550, 2017). "Cervical cancer cell lines also showed a significant negative correlation between KLF4 expression and hypermethylation." (PMID 24551169, 2014). "Epithelial transformation by KLF4 requires Notch1 but not canonical Notch1 signaling, and Notch signaling plays an important role in the development and progression of cervical cancer." (PMID 24551169, 2014). "In the BSQ1 region of the KLF4 promoter, low methylation levels were detected in both cervical cancer and normal cervix tissues (data not shown)." (PMID 24551169, 2014). "However, the mechanism of KLF4 silencing in cervical carcinomas has not yet been identified." (PMID 24551169, 2014). "KLF4 protein expression and promoter methylation also showed significant negative correlation in both cervical carcinoma and normal cervical tissues (P<0.05), suggesting that KLF4 inactivation at the transcriptional level may attribute to its suppression at the protein level." (PMID 24551169, 2014). "The level of expression of OCT4, SOX2, KLF4, C-MYC, and NANOG (OSKM-N) proteins was higher in cervical cancer (CC) samples than in a nontumor sample." (PMID 31885625, 2019).
cardiac hypertrophy (24 papers, 2014 to 2025). "Our study implicated Klf4 and Myh14 to be negative regulators of cardiac hypertrophy under ISO stress." (PMID 27385019, 2016). "Collectively, these prior studies implicated Klf4 and Myh14 as negative regulators of stress-induced cardiac hypertrophy in vivo, which is also supported by our results." (PMID 27385019, 2016). "This study aims to deepen the underlying mechanism of the interaction between KLF4 and SIAT7A in the progression of Ang II‐induced cardiac hypertrophy, with potential implications for the identification of novel therapeutic targets in clinical settings." (PMID 39431583, 2024). "The in vivo and in vitro findings indicate that the overexpression of Siat7A leads to an upregulation of KLF4 levels in cardiomyocytes, thereby promoting cardiac hypertrophy." (PMID 39431583, 2024). "This study seeks to deepen the underlying mechanisms of the KLF4 and SIAT7A interaction in the progression of Ang II‐induced cardiac hypertrophy." (PMID 39431583, 2024). "KLF4 negatively regulates cardiac hypertrophy as a transcriptional control center for cardiac metabolic function and mitochondrial life cycle." (PMID 38516000, 2024). "HDAC Class I downregulates anti-hypertrophy genes including Kruppel-like factor 4 (Klf4) and inositol-5 phosphatase f (Inpp5f), promoting cardiac hypertrophy." (PMID 39596076, 2024). "Oxytocin (OT), a hormone involved in cardiovascular homeostasis, mitigates cardiac hypertrophy by targeting the lncRNA GAS5/miR-375-3p/KLF4 axis to inhibit the PI3K/AKT pathway." (PMID 38516000, 2024). "Taken together, these findings provide additional evidence for the regulatory role of miR-25 in cardiac hypertrophy and fibrosis by regulating KLF4 expression in vitro." (PMID 37569807, 2023). "Simultaneously, the expression of KLF4, a negative regulator of cardiac hypertrophy and fibrosis, was notably decreased." (PMID 37569807, 2023). "This suggests that miR-25 inhibition counteracts the effects of Ang II on cardiac hypertrophy and fibrosis by restoring KLF4 expression." (PMID 37569807, 2023). "Among these, KLF4 was of particular interest because it is highly conserved across species and multiple studies have shown that KLF4 inhibits cardiac hypertrophy and fibrosis by regulating TGF-β, although a contradictory result was also reported." (PMID 37569807, 2023). "To elucidate the role of KLF4 in cardiac hypertrophy and fibrosis, we used two well-established models." (PMID 37569807, 2023). "Mhrt regulated the expression of KLF4 to prevent ERK and KLF4 interaction, hence inhibiting the development of cardiac hypertrophy." (PMID 35224032, 2022). "Genes that suppress cardiac hypertrophy, including KLF4 and INPP5F, are potential therapeutic targets for cardiac hypertrophy." (PMID 35719043, 2022). "The reason of the heart having the lower relative expression level of KLF4 is a vital role of KLF4 in cardiac hypertrophy and atherosclerotic plaque." (PMID 34421986, 2021). "In summary, our study demonstrates that OT ameliorates cardiac hypertrophy by inhibiting PI3K/AKT pathway via lncRNA GAS5/miR-375-3p/KLF4 axis." (PMID 34925023, 2021). "Cardiomyocyte-specific knockout of KLF4 aggravates ISO-induced cardiac hypertrophy, which suggests that control of KLF4 is a potential therapeutic target for cardiac hypertrophy." (PMID 34925023, 2021). "In vivo, cardiac hypertrophy induced by either chronic Ang II infusion or TAC results in significant increased cardiac KLF4 gene expression." (PMID 29970016, 2018). "KLF4 has also been shown to be involved in the pathogenesis and development of cardiac hypertrophy." (PMID 39431583, 2024). "In cardiac muscle, KLF4 is involved in the negative regulation of cardiac hypertrophy." (PMID 37723138, 2023). "Kruppel-like factor 4 (KLF4) plays an important role in cardiac hypertrophy." (PMID 34925023, 2021). "In contrast, Klf4 over-expression significantly blocks cardiac hypertrophy." (PMID 28977827, 2017).
cardiac hypertrophy (continued). "Furthermore, LY194002, an inhibitor of PI3K, abrogated sh-Klf4-evoked cardiac hypertrophy." (PMID 34925023, 2021). "This led to a dose-dependent restoration of downstream effector genes KLF4 and INPP5F, significantly improving cardiac hypertrophy parameters and alleviating myocardial hypertrophy." (PMID 40786032, 2025). "We found that KLF4 expression was elevated by Ang II stimulation, concomitant with increased expression of SIAT7A and induction of cardiac hypertrophy." (PMID 39431583, 2024). "This interaction establishes a positive feedback loop between KLF4 and the SIAT7A‐Sialyl‐Tn, there by promoting Ang II induced cardiac hypertrophy." (PMID 39431583, 2024). "In vivo studies have shown that KLF4 can modulate isoproterenol-induced cardiac hypertrophy by regulating myocardin (MYOCD) expression and activity, and cardiomyocyte-specific knockdown of KLF4 exacerbates hypertrophy." (PMID 38516000, 2024). "In conclusion, our present study identified an interaction between KLF4 and SIAT7A‐Sialyl‐Tn during the development of myocardial hypertrophy." (PMID 39431583, 2024). "Mhrt increased the expression of KLF4 through direct binding to miR-145a-5p or inhibiting phosphorylation of KLF4, to prevent ERK and KLF4 interaction, hence inhibiting myocardin expression and the development of cardiac hypertrophy." (PMID 35224032, 2022). "In cardiac hypertrophy HDAC I downregulates the anti-hypertrophy gene expression, including Kruppel-like factor 4 (Klf4) and inositol-5 phosphatase f (Inpp5f), and promote the development of cardiac hypertrophy." (PMID 35958418, 2022). "The findings showed that OT significantly attenuated cardiac hypertrophy, increased expressions of lncRNA GAS5 and KLF4, and decreased miR-375-3p expression." (PMID 34925023, 2021). "Klf4 is a novel anti-hypertrophic transcriptional regulator and mediates the HDAC inhibitor-induced prevention of cardiac hypertrophy and Nppa upregulation." (PMID 33854108, 2021). "Among these genes, Klf4 alone had a significant cis-eQTL at SNP rs27794497 (p-value = 5.9 x 10−5) and was significantly correlated with LVM hypertrophy at week 3 (bicor = -0.3, p-value = 0.0088)." (PMID 27385019, 2016). "Notably, KLF4 expression increased prior to SIAT7A, suggesting KLF4 initiates SIAT7A activity during Ang II‐induced cardiac hypertrophy." (PMID 39431583, 2024). "This resulted in the identification of KLF-4 interactions with genes like GATA4, MEF2C, TBX5, NKX2.5, and SRF, all of which are known regulators of cardiac hypertrophy and pro-hypertrophic pathways." (PMID 38672763, 2024). "Moreover, KLF4 knockdown decreased expression of SIAT7A and Sialyl‐Tn induced by Ang II stimulation, thereby inhibiting cardiac hypertrophy." (PMID 39431583, 2024). "The expressions of cardiac hypertrophy markers (B-Natriuretic Peptide, BNP and β-myosin heavy chain, β-MHC), long non-coding RNA Growth (LcRNA) Arrest-Specific transcript 5 (lncRNA GAS5), miR-375-3p, and Kruppel-like factor 4 (Klf4) were detected by qRT-PCR." (PMID 34925023, 2021). "Our study revealed the role of lncRNA GAS5 and KLF4 in cardiac hypertrophy in an in vitro model, not in an in vivo one." (PMID 34925023, 2021). "Of these only KLF4, KLF5, KLF10, KLF11 and KLF15 have been studied in cardiac hypertrophy." (PMID 29970016, 2018). "In other words, the higher the Klf4 expression, the lesser the degree of LVM hypertrophy." (PMID 27385019, 2016). "MHRTincreases KLF4 expression by either directly interacting withmiR-145a-5p or by forming a complex with KLF4 that prevents its phosphorylation.This action inhibits the binding of ERK to KLF4, which subsequently reducesmyocardin expression and lessens myocardial hypertrophy." (PMID 40776938, 2025). "In addition, KLF4 may be initially activated and subsequently trigger the expression of SIAT7A in the cardiac hypertrophy process induced by Ang II." (PMID 39431583, 2024).